MYC (MYC proto-oncogene, bHLH transcription factor)
Diseases named in the same sentence as MYC in open-access papers (continued):
Sharing a sentence is not in itself a finding about the gene and the disease.
cancer (continued). "In multiple cancers, we identified that RRM2B and/or MYC were amplified as part of an amplicon with multiple other 8q-genes (list of cancer relevant genes and gene ontology classification)." (PMID 33868369, 2021). "Through the gradual understanding of the carcinogenic properties of abnormal c-MYC expression, c-MYC has become a therapeutic target for many malignant tumors." (PMID 34950208, 2021). "For example, in different cancer types the let-7 miRNA family alone modulates the abundance of CCND1, CDK4 as well as MYC." (PMID 33748099, 2021). "MANOVA on these genes reveals that this combined set of 7 genes (MYC, CD40LG, CCL4, IL7, TCF4, CCR7 and FASLG) is together statistically significantly reliant on both time post-exposure (p = 0.042) and cancer type (p < 0.001)." (PMID 33941218, 2021). "Pin1 regulates the self-renewal of Cancer Stem Cells (CSCs) by maintenance the stability of Nanog, octamer-binding protein 4 (OCT4), and MYC." (PMID 34805153, 2021). "The SRC oncogene was followed by MYC, ERBB/EGFR, and RAS oncogenes whose identification in diverse human cancers consolidated the view of cancer as a genetic disease." (PMID 34070384, 2021). "Increased expression levels of LGR5, PROM1, KLF4, SOX2, and MYC in HGD and cancerous tissues support the malignant phenotype and the existence of cancer stem cells and demonstrate that they can be used to assess diagnosis and prognosis." (PMID 34452555, 2021). "ODC is a direct transcription target of MYC oncoproteins and is overexpressed in MYC- and MYCN-driven cancers." (PMID 34068137, 2021). "Previous reports have shown that oncogenic KRAS promotes cancer cell metabolism and proliferation by altering the AKT, MTOR, E2F, and MYC pathways." (PMID 34003553, 2021). "In highlighting the importance of intrachromosomal gene location, it is worth pointing out the case of the over-expressed genes MYC and CCND1 in cancer cells located at the edges of their chromosome territories." (PMID 34831011, 2021). "MYC and CCND1 are well-known targets of YAP, and their contribution to cell proliferation, cell cycle, and cancer progression is well-established." (PMID 33514403, 2021). "Several studies in mouse models have demonstrated the importance of MYC in KRAS-driven oncogenesis and genetic suppression of MYC impairing the growth of KRAS-driven cancer cells." (PMID 34944853, 2021). "HPV integration is most frequently detected in genic regions, most often cancer-related genes, such as oncogenes (e.g., TP63, MYC, ERBB2) or tumor suppressor genes (e.g., BCL2, FANCC, HDAC2, RAD51B, CSMD1) and to a lesser extent in miRNA regions." (PMID 34439243, 2021). "Within community 2, we also identified increased expression of regulators of cell proliferation (CENPE, MKI67, TOP2A, UBE2C, guanine), cancer, and pluripotency (DNMT3B, DPPA4, MYC, POU5F1, CRABP2)." (PMID 33771987, 2021). "HDACi (such as SAHA) were recently shown to induce acetylation of MYC at K323, resulting in MYC downregulation at both mRNA and protein level, thus releasing expression of target genes, including TRAIL, and leading to cancer cell apoptosis." (PMID 33801599, 2021). "Thus, our findings suggest that SQLE may be a potential therapeutic target in MYC-driven cancers." (PMID 33791309, 2021). "Therefore, miRNAs may serve as potential therapeutic targets against MYC-driven cancers." (PMID 33718147, 2021). "The putative mechanisms of let7 down-regulation in cancer include not only genetic alterations, but also regulation of RAS and MYC oncogenes, direct targeting of DICER mRNA and cell proliferation control in a cyclin-dependent manner." (PMID 33802346, 2021).
cancer (continued). "Given that SENP1 positively regulates MYC levels and activity, SENP1 is an interesting cancer therapeutic target." (PMID 34178666, 2021). "MYC is one of the nuclear factors most often associated with dysregulated transcription, as genetic abnormalities of the MYC family of oncogenes (C-MYC, MYCN, and MYCL1) are among the most common alterations in human cancer." (PMID 34788094, 2021). "Here, we report that the coordinated actions of MYC, PARP1, and ATM assist cancer cells in acquiring cisplatin resistance by BIN1 deficits." (PMID 34948122, 2021). "Based on the association between SCRIB and the Wnt/β-catenin pathway, recent reports have shown the molecular relationship between MYC, FAM83H, SCRIB, and the Wnt/β-catenin pathway in human cancers." (PMID 33803371, 2021). "In other reports, c-MYC, SOX2, and NF-κB have been shown to regulate LIN28 expression in different model systems, including cancer." (PMID 34572725, 2021). "The lncRNA PVT1 was found to be related to the MYC oncogene, and both are located within the 8q24.21 genomic region; PVT1 undergoes a copy number increase in many human cancers." (PMID 34940760, 2021). "From the remaining five, only the roles of MYC and CCND1 as inducers of cell proliferation and cancer progression in connection with YAP were very well established." (PMID 33514403, 2021). "This approach to downregulate an oncogene has been best studied for the c-MYC promoter G4, in which the c-MYC protein is overexpressed in a majority of human cancers." (PMID 34541539, 2021). "We found eight MAPK pathway genes (including MYC, WNK1 and PXN) that are classifiable as “common essential” (see the “Methods” section) among all cancer cell lines." (PMID 33398072, 2021). "It is suggested that the simultaneous overexpression of miR-1252-5p or downregulation of MYC in MKN-45 and MKN28 cell lines can reverse the cancer-promoting effect of circABCB10." (PMID 34950208, 2021). "c-Myc is the most essential member of the MYC oncogene family and is involved in a variety of biological functions of cancer, including proliferation, metastasis, apoptosis, differentiation, and metabolism." (PMID 34167558, 2021). "They corresponded to cell fate determination, cell cycle activation, epigenetic modifications, DNA damage response, as well as cancer-related pathways including Wnt/β-catenin, PI3K/AKT/mTOR, Slit2/Robo1, MYC, and ErbB2-ErbB3 axes." (PMID 33747361, 2021). "Interestingly, among the 33 cancer types studied in TCGA, only thymoma, thyroid carcinoma, chromophobe renal cell carcinoma, acute myeloid leukemia, papillary renal cell carcinoma, and pheochromocytoma/paraganglioma have infrequent amplifications of either of the three MYC paralogs." (PMID 34503295, 2021). "A total of 41% of pancreato-biliary ITPNs showed a heterogeneous amplification of that region, which contains different cancer-specific genes (e.g., oxidation resistance 1 OXR1, and the prominent proto-oncogene MYC)." (PMID 34205964, 2021). "MYC, SOX2, JUN, or ARNT was significantly correlated with THBS2 in most cancers, including COAD and PAAD." (PMID 34804159, 2021). "HDAC inhibitors have demonstrated strong efficacy in pre-clinical models of MYC and MYCN-driven cancer." (PMID 33658627, 2021). "It has been observed that overexpression of c-MYC is a frequent abnormality in human HCC; therefore, it has been considered to be a therapeutic target of great importance in other types of cancer." (PMID 34641286, 2021).
cancer (continued). "The MYC and STAT3 oncoproteins are widely overexpressed or activated across human cancers and the mTORC1/S6K1 pathway is frequently stimulated in malignancies." (PMID 35095503, 2021). "As such, several key players of glutamine metabolism are requisites for the growth of MYC-driven cancer cells: GLS1, transaminases, and GFAT being particularly compelling targets in the context of MYC oncogene activation." (PMID 34503295, 2021). "For example, as an ibrutinib-venetoclax nonresponder, Patient B was clearly separated from the ibrutinib-sensitive patients, particularly in the manifestation of cancer hallmarks such as OXPHOS, mTORC1, G2/M checkpoint, and MYC." (PMID 34001881, 2021). "The expression of the stemness-associated markers OCT4, SOX2, NANOG, KFL4 and c-MYC by LA at the mRNA and protein level, and the unique expression patterns suggest a putative presence of CSC subpopulations within LA, which may be a novel therapeutic target for this cancer." (PMID 34685477, 2021). "Aberrant expression of MYC is observed in many human cancers including CRC11, but the prognostic value of MYC in CRC remains debatable." (PMID 32591507, 2020). "It was recently shown that the let-7 family members tend to act as tumor suppressors by supressing oncogenes such as RAS, c-MYC, BCL-XL, NF-kB, and High Mobility Group A2 (HMGA2) in various cancers." (PMID 33519805, 2020). "During this process, the oncogenes c-MYC, KRAS, and YAP upregulate GLUT1 expression in cancer cells." (PMID 33081387, 2020). "Among those genes, the MYC oncogene was one of the top EREG-regulated genes and codes for a transcription factor that is overexpressed in many human cancers." (PMID 32929368, 2020). "Consistent with the idea that WRN is required for cancer cell proliferation, WRN knockdown suppresses anchorage-dependent growth of cancer cells in vitro and MYC-induced oncogenesis in animal models." (PMID 33054770, 2020). "Without expression of these proteoglycans, there is decreased regulation of several established and potent oncogenic pathways such as EGFR, TGFβ, MYC, and c-MET that can lead to cancer growth and metastasis." (PMID 32553107, 2020). "First, XPO1 is frequently overexpressed in human cancers, while XPO1 suppression has been shown to reduce the protein levels of driver oncogenes, such as MYC and EGFR, in multiple cancer types." (PMID 32487143, 2020). "Emerging evidence suggests that MYC and HIF also cooperate to promote cancer cell growth and progression." (PMID 33251216, 2020). "Another strategy is the downregulation of MYC by CBP/p300 inhibition at its bromodomain using I-CBP112, which inhibits the growth of cancer cells in human AML cell lines with MLL-AF9 translocation." (PMID 33302406, 2020). "EIF4E is modestly altered in cancers at the DNA level, with a profile resembling the tumor suppressor RB1 more than the MYC oncogene." (PMID 33266490, 2020). "Most likely, these factors cooperate with MYC to maximize SLC7A5/SLC43A1 (and additional transporters) expression and EAA uptake in human cancers." (PMID 32651356, 2020). "MYC invariably promotes expression of critical enzymes involved in aerobic glycolysis, such as HK2 and LDHA, making cancer cells more vulnerable to glycolysis inhibition." (PMID 32651356, 2020). "MYC amplification and high CLK2 expression in cancer cells are considered predictive of the response to a CLK inhibitor." (PMID 33064779, 2020). "In cancer cells, the oncogene EPIC1 interacts with MYC and regulates the occupancy of MYC on target promoters." (PMID 32924276, 2020).
cancer (continued). "We examined if MYC and TWIST1 cooperated in human tumorigenesis by examining 9502 human patients with 33 different cancers from a TCGA study and 144 HCC patients with metastatic HCC." (PMID 31933479, 2020). "Increasing number of studies are gradually clarifying the key signalling pathways involved in cancer initiation, progression, and metastasis, including the PI3K-Akt signalling pathway, MYC signalling pathway and so on." (PMID 33344083, 2020). "Further, combined MYC and TWIST1 expression correlated strongly with CCL2 and IL13 in the pan-cancer cohort (p=1.4×10−109)." (PMID 31933479, 2020). "In cancer, PIN1’s regulation of MYC has been shown to affect oncogenic transformation, proliferation, redox maintenance, and cell survival." (PMID 32300594, 2020). "In the COSMIC cancer census gene list, the MYC, NSD3 and KAT6A genes on chr8 have been amplified in cancer." (PMID 32512761, 2020). "The MYC is a classical oncoprotein in various cancers, including LC, and an in-depth investigation demonstrated the significance of the hsa_circRNA_103809/miR-4302/ZNF121/MYC regulatory in LC progression." (PMID 32071550, 2020). "MYC(c-myc) had been discovered as an mRNA target of METTL3-mediated m6A modification by high-throughput RNA-Seq and m6A-Seq in different types of cancer 15,16." (PMID 32284755, 2020). "The aaRS profiles are compared to genes with established roles in cancer, including a tumor suppressor (RB1), a proto-oncogene (MYC), and a translation factor (eIF4E)." (PMID 33266490, 2020). "(a) Disease-free survival in pan-cancer TCGA cohort of 9502 patients from 33 cancers stratified by median MYC+TWIST1 expression (first KM curve) and median MYC+TWIST1+ CCL2+IL13 (second KM curve)." (PMID 31933479, 2020). "MYC also induces the expression of other genes, like Adam19, Thop1, Adora2b, Hepsin, and Amphiregulin (AREG) which are then involved in cancer invasion and migration." (PMID 33081056, 2020). "With the help of cofactors, IGF2BPs promote the stability of thousands of potential target mRNAs, hinder miRNA-induced RNA decay and improve the expression of oncogenes (MYC, Actin, Lin28, SRF) to play a carcinogenic role in cancer." (PMID 32653017, 2020). "As silencing of BRD4 downregulates the expression of the MYC (v-Myc Myelocytomatosis Viral Oncogene Homolog) oncogene, JQ1 is a potent anti-cancer molecule." (PMID 32414180, 2020). "Triple-negative breast cancer cells overexpress MYC and MCL1, which together maintain chemotherapy-resistant cancer stem cells by enhancing mitochondrial OXPHOS, increasing ROS production, and inducing HIF1α expression." (PMID 32397535, 2020). "MYC family oncoproteins MYC, MYCN, and MYCL are deregulated in diverse cancers and via diverse mechanisms." (PMID 33425720, 2020). "Among the regions shortlisted using our approach, we found some previously characterized cancer-related lncRNAs such as PVT1, localized downstream of the MYC locus, or CCAT1/CARLo-5, located in an amplified region upstream of the MYC locus." (PMID 32858747, 2020). "In cancer cells, BRD4 is disproportionately enriched at certain key oncogenic genes, such as c-MYC, and selectively upregulates their expression to drive cellular proliferation." (PMID 32575711, 2020).
cancer (continued). "In colon and breast cancer cells, miR-145 reduces the levels of several oncoproteins, such as c-MYC and VEGF, decreasing cell proliferation and the angiogenic potential of cancer cells." (PMID 33081171, 2020). "Various oncogenic pathways have been reported to affect expression of MHC-I, β2M, and other APM components in cancer, including the MAPK-, epidermal growth factor receptor (EGFR), HER2, c-MYC, and n-MYC pathway." (PMID 32630675, 2020). "Deregulation of the MYC oncogene, along with inactivation of PP2A, are two frequent events in cancer." (PMID 32110991, 2020). "Overexpression of MYC correlates with expression of cellular transporter of glutamine, SLC1A5, and enhances glutamine consumption in cancer cells." (PMID 33117715, 2020). "The abnormal expressions of NOS2, DUOX2/DUOXA2, ESR1, EGFR, MYC, and AKT1, which are being discussed in this study, have been confirmed to be related to cancer." (PMID 33299870, 2020). "The genomic identification of significant targets in cancer analyses (GISTIC) led to identify recurrent focal deletions (3p14.2 (FHIT), 11q11, and 4q13.2) and focal amplifications (17q13 (ERBB2), 8q24.21 (MYC), 3q26.31 (PIK3CA, TRAIL), 8q24.22, 8q21.13)." (PMID 32647357, 2020). "We analyzed normal tissue from wild-type mice and a set of prostate lesions from Hi-MYC mice with low-grade prostate intraepithelial neoplasia (Low-PIN), high-grade PIN (high-PIN), carcinoma in situ (CIS), and invasive cancer." (PMID 32313005, 2020). "MAPK signalling pathway (JUN, RAC1, MAPK8, MYC and FOS) and transcriptional misregulation in cancer (CDKN1A, MYC and FOXO1)." (PMID 32457348, 2020). "In contrast to MYC and RB1, which are predominantly modified at the DNA level, aaRSs seem to be mostly dysregulated at the transcriptional level in cancer." (PMID 33266490, 2020). "Eight mRNA markers (MYC, VEGF, CDX2, CD133, CEA, CK19, EpCAM, and CD24) were found to be more abundant in EVs derived from cancer cell lines compared to control cell lines." (PMID 32042310, 2020). "However, the IC50 value of cancer cell death was similar to those of other cell lines, implying that the anti-cancer activity of CKD-581 may have resulted not only from MYC reduction, but other mechanisms such as DNA damage and decreased expression of anti-apoptotic proteins in DLBCL cell lines." (PMID 32575557, 2020). "Several studies have shown that LIN28 proteins are overexpressed in different types of cancers (colorectal, breast, and ovarian), where the function of let‐7 as tumour suppressor against RAS or MYC is lost." (PMID 33391635, 2020). "For example, c-MYC activates the expression of ASCT2 and GLS-1 under the induction of lactic acid, leading to elevated glutamine uptake and catabolism in cancer cells." (PMID 33489906, 2020). "In this review, we focus on the current understanding of the molecular interplay between MYC and HIF in cancer cell metabolism, growth and progression as well as its potential implication in cancer therapy." (PMID 33251216, 2020). "Tissue microarray analysis of primary tumors indicated a high correlation between PVT1 and MYC expression, providing strong evidence for cooperation between PVT1 and MYC in different human cancers." (PMID 32992461, 2020). "Among the most enriched pathways between H3.3K27M-driven mouse cancers and human DIPGs were target genes of RAS/MAPK and MYC." (PMID 33277484, 2020). "We observed MYC and AKT1 mRNA expression was consistent with copy number amplification across cancer types." (PMID 32635458, 2020).